IL10 (interleukin 10)
Diseases named in the same sentence as IL10 in open-access papers (continued):
Sharing a sentence is not in itself a finding about the gene and the disease.
periodontitis (continued). "In human studies, CD19+CD24+CD38+ Bregs were more prevalent in the peripheral blood of patients with stage II periodontitis and were positively correlated with elevated levels of IL-10, TGF-β, and IL-35." (PMID 41289041, 2025). "Clinical samples from patients with periodontitis showed elevated levels of immunoreactive B10 cells and IL-10 expression in inflamed gingival tissues." (PMID 41289041, 2025). "Progranulin and IL‐37 can promote the high expression of IL‐10 in M2 macrophages, which can alleviate the progression of periodontitis in mice, suggesting that the remission of periodontitis is related to IL‐10." (PMID 41181974, 2025). "IL-10 can interfere with tissue homeostasis by pro-inflammatory cytokine suppression, thus playing a positive role in preventing the progression of periodontitis and increasing its stability." (PMID 39964474, 2025). "The Fas/FasL pathway similarly mediates apoptosis, with IL‐10 enhancing this process by activating caspase‐8 and regulating immune homeostasis in periodontitis." (PMID 41399014, 2025). "One study constructed a mouse periodontitis model; compared with the control mice, the area of bone resorption in the alveolar bone of mice injected with IL-10 was reduced, suggesting that IL-10 is involved in inhibiting bone resorption." (PMID 40922724, 2025). "Transfection with microRNA-466l enhanced IL-10 levels in healthy and periodontitis-isolated periodontal ligament stem cells and inhibited cell proliferation, regardless of the periodontal ligament stem cells’ origin." (PMID 41289041, 2025). "The results showed that PA significantly reduced IL-1β, IL-6, TNF-α, CRP, and LPO levels and increased IL-10 levels in the periodontitis group; moreover, the histological analysis showed reduced inflammatory infiltrate and less fiber degradation." (PMID 40422620, 2025). "Salivary and GCF Metrnl, IL-1β, and IL-10 levels were evaluated in patients with stage III periodontitis." (PMID 39964474, 2025). "Salivary IL-17 and IL-10 have been shown to differentiate healthy individuals from those with periodontitis and to discriminate among disease stages." (PMID 41440349, 2025). "In conclusion, our findings demonstrate that treatment with IL10 gene modified MSCs is a more powerful cell therapy approach for periodontitis and has more benefits compared to control MSCs." (PMID 41181974, 2025). "After a thorough quality evaluation, we established overexpressed IL‐10‐MSCs and used them for the first time in a rat periodontitis repair model." (PMID 41181974, 2025). "In the following section, we will discuss recent developments on the role of IL-10 and IL-10-expressing regulatory B cells (Breg) in the pathogenesis of periodontitis." (PMID 41289041, 2025). "Conversely, IL-10, an anti-inflammatory cytokine known for its regulatory effects on immune responses, exhibited elevated levels in periodontitis patients at baseline." (PMID 40542868, 2025). "In the present study, we treated the periodontitis using IL‐10‐MSCs to chronically release the IL10 in injured sites, leading to alleviating periodontal inflammation." (PMID 41181974, 2025). "Evidently, IL‐10‐MSCs successfully restored the alveolar bone resorption and regenerated thick fibre cells at injured sites in a rat periodontitis model." (PMID 41181974, 2025). "Administering exosomes derived from M2 macrophages to a mouse periodontitis model has been shown to prevent pathological alveolar bone resorption and to increase IL‐10 mRNA expression." (PMID 41181974, 2025). "Similar findings were reported in the Chinese Han population, where individuals with the IL-10–592 AA and -819 TT genotypes showed higher frequencies of periodontitis compared with healthy controls after adjusting for age, gender, and periodontal status." (PMID 41289041, 2025). "The GCF IL-10 concentrations were significantly lower in the gingivitis and periodontitis groups than in the healthy group (p = 0.001)." (PMID 39964474, 2025).
periodontitis (continued). "It was proposed to use IL-10 and IL-10 Rα to attenuate excessive IL-17 activity, thereby reducing the clinical expression of periodontitis and ABL and maintaining homeostasis." (PMID 41289041, 2025). "Specifically, Allium sativum (garlic) extract has been shown to upregulate anti-inflammatory cytokines, such as IL-10 and IL-13, which significantly reduce alveolar bone resorption in experimental periodontitis models." (PMID 41477399, 2025). "IL-10 is an anti-inflammatory cytokine that can reduce the inflammatory response in patients with periodontitis." (PMID 40282186, 2025). "The levels of IL-10 and IL-18 were significantly higher in the advanced periodontitis group than in the healthy or mild periodontitis groups." (PMID 41289041, 2025). "Herein, human MSCs stably expressing interleukin‐10 (IL‐10‐MSCs) were established and evaluated for their performance in treating ligature‐induced periodontitis rats." (PMID 41181974, 2025). "This will help us further clarify its mechanism of action and gain a more comprehensive understanding of the therapeutic effect of IL‐10‐MSCs in the treatment of periodontitis." (PMID 41181974, 2025). "These IL‐10‐MSCs and blank vector transfected MSCs were transplanted into rat ligature‐induced periodontitis models by repeated injections via the periodontal and tail veins." (PMID 41181974, 2025). "Experimental periodontitis models have confirmed a significant increase in CD45+IL-10+ cells within diseased gingiva compared with healthy controls." (PMID 41289041, 2025). "Porphyromonas is a major pathogen of chronic periodontitis, and some experiments have shown that Porphyromonas induces IL-17 and IL-10-mediated inflammatory responses." (PMID 40442807, 2025). "Its expression and IL-10 mRNA expression are reduced in periodontal ligament stem cells derived from periodontitis-affected teeth." (PMID 41289041, 2025). "Gingival tissues of patients with periodontitis exhibited high levels of IL-10 and RANK transcripts, as well as an increased IL-17/IL-10 ratio." (PMID 41289041, 2025). "In an experimental periodontitis model, adoptively transferred IL-10-producing B cells demonstrated the ability to reduce local IL-17 and RANKL expression and alleviate alveolar bone resorption by reducing periodontal osteoclastogenesis." (PMID 39253090, 2024). "Conversely, a significant relationship between IL-10 and periodontitis was established in mixed populations." (PMID 39336814, 2024). "In the current study, analysis of the data showed that salivary IL-1β, IL-10, and IL-1β/IL-10 ratio had high accuracy in differentiating periodontal health from periodontitis." (PMID 39445112, 2024). "The IL-10 and IL-18 levels were significantly higher in the periodontitis group than in controls (p < 0.001, p < 0.001, respectively)." (PMID 39080003, 2024). "This study investigates the influence of SNPs in the IL-10 gene at positions −592 (rs1800872) C>A and −1082 (rs1800896) T>C (also referred to as 1082A>G) on the severity of periodontitis in a cohort of Bulgarian patients." (PMID 39336814, 2024). "OPG and RUNX2 expression increased after GelMA action, while IL-10 decreased considerably compared to the periodontitis group; this expression was more pronounced in the RvD1 complexed with GelMA group." (PMID 39861667, 2024). "This study was designed to determine the potential of IL-17 and IL-10 to diagnose patients with periodontitis by measuring their concentrations in saliva and also individuals with healthy gingiva along with the presence of smoking as a risk factor." (PMID 37172945, 2024). "In this group of Portuguese individuals, we found lower levels of IL-23 and IP-10 (CXCL10) in periodontitis patients but higher levels of IL-10." (PMID 39125970, 2024).
periodontitis (continued). "Interestingly, the IL-1β/IL-10 ratio showed an improved diagnostic potential (AUC of 1, p < 0.0001) to discriminate between periodontal health from unstable periodontitis (cutoff value >1.35) and stable periodontitis from unstable periodontitis (cutoff value >1.55)." (PMID 39445112, 2024). "One study reported increased serum levels of IFN-gamma, TNF, and IL-10 in patients with periodontitis as compared to healthy controls." (PMID 39253090, 2024). "High density within CHD1 as well as JMJD2A is observed in periodontitis which accurately corresponds with the in vitro model- neutrophils exposed to IL-10." (PMID 38745328, 2024). "Among these cells, neutrophils can inhibit the inflammatory response in chronic periodontitis by killing bacteria, releasing interleukin-10 (IL-10) and accelerating tissue destruction by promoting the inflammatory response through multiple pathways." (PMID 38308306, 2024). "IL-10, known as an anti-inflammatory cytokine, plays a complex role in the pathogenesis of periodontitis." (PMID 39445112, 2024). "Common inflammation biomarkers in saliva and plasma in patients with DM2 and periodontitis; p1 = 0.003 (IL-10) and p2 < 0.001 (IL-4)." (PMID 38727455, 2024). "In this study, the periodontitis group had significantly higher IL-10 levels than the healthy control group." (PMID 39080003, 2024). "In turn, neutrophils isolated from periodontitis were characterised by a high level of H3S10p, which corresponds with neutrophils exposed to IL-10." (PMID 38745328, 2024). "The application of EV therapy in periodontitis presents significant clinical opportunities by demonstrating how EVs can influence key cytokines like IL-5, IL-6, IL-17A, IL-10, and TNF-α." (PMID 38891939, 2024). "IL-10, while traditionally considered an anti-inflammatory cytokine, has been found to have complex roles in periodontitis." (PMID 38891939, 2024). "Our study emphasizes the importance of further research involving larger and more diverse populations to validate the relevance of IL-10 SNPs as markers for periodontitis severity within the Bulgarian population and beyond." (PMID 39336814, 2024). "IL-10 is an immunoregulatory cytokine critical to the balance between microbial and inflammatory responses in periodontitis." (PMID 38627806, 2024). "The aim of this research is to assess the effectiveness of 0.2% HA gel on periodontal parameter, quantity ofPgandFn, and the levels of proinflammatory cytokine, IL-1β, and anti-inflammatory cytokine, IL-10, in DM patients with periodontitis." (PMID 39074834, 2024). "The IL-1β/IL-10 ratio in saliva exhibits a valuable potential for diagnosing periodontitis and in discriminating periodontitis stability." (PMID 39445112, 2024). "Periodontitis-derived circulating neutrophils were used as a physiological response of neutrophils to IL-10." (PMID 38745328, 2024). "We highlight that curcumin significantly increases IL-4 concentrations 42 and insignificantly IL-10 levels 53 in subjects with periodontitis." (PMID 39912085, 2024). "Another study reported a trend toward higher IL-10 levels in older patients as compared to younger subjects with periodontitis." (PMID 39253090, 2024). "In a related study on Azadirachta indica (neem), the extract was found to increase IL-10 production, leading to improved clinical outcomes in periodontitis-induced animal models." (PMID 39539670, 2024). "In this study, the IL-1β/IL-10 ratio exhibited high sensitivity and specificity for potentially discriminating periodontitis from healthy groups as well as for distinguishing unstable from stable periodontitis groups." (PMID 39445112, 2024). "To date, specific genetic variations consistently associated with periodontitis in certain populations include those within ANRIL, COX2, IL1, IL10, and DEFB1 genes." (PMID 39650553, 2024).
periodontitis (continued). "In this study, the level of IL-10 was lower in periodontitis patients than in peers with healthy periodontium; this finding is in accordance with what has been reported in the literature." (PMID 39445112, 2024). "The highest mean value of the anti-inflammatory cytokine IL-10 was observed in the positive control group, which consisted of rats induced with periodontitis and treated with 0.2 % CHX, measuring 530.941 ± 193.601 pg/mL." (PMID 39539670, 2024). "In summary, our study found that IFNβ can inhibit the progression of chronic periodontitis and protect periodontal tissues via the induction of IL10 production through ISG15." (PMID 37876725, 2023). "We first examined the immune status associated with periodontitis by comparing the levels of IL-17 and IL-10 from serum samples of healthy normal mice and periodontitis mice." (PMID 37490712, 2023). "The FoxP3 mRNA and soluble IL-10 levels from the group with the T cells co-cultured with periodontitis BM-MSCs were drastically diminished to the extents even lower than the control T cells without BM-MSC co-culturing." (PMID 37490712, 2023). "In a similar way, some authors suggest higher salivary IL-10 levels in periodontitis than in healthy individuals, whereas others have described just the opposite." (PMID 37246231, 2023). "IL-4 and IL-10 in the periodontitis groups were significantly lower than the healthy group (p < 0.0001) and barely improved following SRP up to the level of the healthy group." (PMID 37246231, 2023). "The results of this study demonstrate cytokine dynamics of IL-1β, TNF-α, and IL-10 in periodontitis, especially in older people." (PMID 37623272, 2023). "It should be pointed out that periodontitis fosters a proinflammatory microenvironment, and the levels of IL-1β, IL-4, IL-10, and IL-17A were significantly higher in diseased sites than healthy sites in the same oral cavity from periodontitis patients." (PMID 36949458, 2023). "In mice with periodontitis, the increased Th17-related genes (i.e.,Il6,Il17a, andRorγt), and Treg-related genes (i.e.,Foxp3,Il2,Il10,Ctla4,Cd25, andGitr) were detected in cervical lymph nodes and spleen." (PMID 37226540, 2023). "The aim of the present study was to investigate any shifts in personalized antimicrobial peptide (LL-37) and cytokine (IL-4, IL-6 and IL-10) profiles in GCF in periodontitis patients subsequent to SRP." (PMID 37246231, 2023). "The investigation showed significant differences in three cytokines, IL-6 (P < 0.01), IL-10 (P < 0.01), and IL-8 (P < 0.0001), between non-periodontitis and periodontitis patients." (PMID 39697803, 2023). "The observed downregulation of IL-10 in the salivary EVs derived from periodontitis suggests a protective response in healthy individuals, aiming to prevent disease." (PMID 39697803, 2023). "This study aimed to clinically analyze the periodontal status and cytokine levels of IL-1β, TNF-α, and IL-10 in older people and adults with periodontitis." (PMID 37623272, 2023). "Akk or Amuc_1100 ameliorate porphyromonas-gingivalis-induced alveolar bone loss by promoting M2 macrophage polarization and improving the production of IL-10 in the gingival tissues of mice, eventually repressing periodontitis." (PMID 36835309, 2023). "In contrast, IL-10 has been reported to be involved in the pathogenesis of periodontitis, as it downregulates the immune response." (PMID 38033572, 2023). "The serum level of IL-17 from the periodontitis group was significantly up-regulated, in comparison to the control healthy group; while that of IL-10 was considerably lower." (PMID 37490712, 2023). "In this study, we aimed to clinically analyze the periodontal status and the cytokine levels of IL-1β, TNF-α, and IL-10 in older people and adults with periodontitis." (PMID 37623272, 2023). "The role of IL-10 in the resolution of inflammation was further supported by our findings in neutrophils isolated from the patient with periodontitis." (PMID 35757755, 2022).
periodontitis (continued). "On the other hand, the anti-inflammatory cytokine IL-10 plays an important role in suppressing the progress of periodontitis and regulating bone metabolism." (PMID 36050950, 2022). "While the levels of IL-10 and IL-13, which are anti-inflammatory cytokines that regulate immune responses, decreased in the animal model of periodontitis, the levels of the same biomarkers increased in the group orally administered TEES-10®." (PMID 36005241, 2022). "Many studies reported the positive role of IL-10 in preventing periodontitis progression and promoting its stability." (PMID 35368315, 2022). "Here, we demonstrate the effect of M2-Exos on inducing BMSCs toward the osteoblasts and inhibiting BMDM toward the osteoclasts via exosomal IL-10 mRNA, as well as inhibiting bone resorption during periodontitis." (PMID 35248085, 2022). "It is interesting to note that in the context of periodontitis, especially the aggressive form of periodontitis, the plasma concentration of IL-10 is lower than that in healthy patients." (PMID 34383142, 2022). "A research study investigated IL-1β, IL-6, MMP-8, and IL-10 levels in healthy as well as periodontitis patients and found that IL-1β and IL-6 concentrations were significantly higher in periodontitis patients." (PMID 36289921, 2022). "Multiple logistic regressions revealed that that IL-10-592 AA, -819 TT and ATA/ATA genotype conferred a slight increase in the risk for chronic periodontitis in the Chinese population after adjustment for age, gender and periodontal status." (PMID 35454140, 2022). "A number of retrospective studies demonstrated a correlation between polymorphisms of interleukins IL-1a, IL-1b, IL-1RN, IL-6, IL-10 as well as TNF-a and the incidence of periodontitis and peri-implant disease." (PMID 35819566, 2022). "In vivo experiments further showed that M2-Exos reduced alveolar bone resorption in mice with periodontitis via IL-10/IL-10R pathway." (PMID 35248085, 2022). "Compared with the periodontitis group, the levels of IL-17A, IL-10 were downregulated and IL-6,TGF-β1 were upregulated in the SPRC groups." (PMID 35087796, 2021). "In patients with periodontitis, inflammatory markers (IL-6, IL-10, TNF-α, C-reactive protein, and ALP) in the gingival crevicular fluid are increased and directly correlated with the severity of the disease." (PMID 33430249, 2021). "Increased immunosuppressive IL-10 cytokines produced by polymorphonuclear neutrophils were observed among periodontitis patients and the interaction of such neutrophils with regulatory T cells stimulated with lipopolysaccharide induced the production of IL-10." (PMID 34950607, 2021). "Migration of B10 cells in periodontitis resulted in increased IL-10, decreased IL-17 and RANKL, regulating local host immune response by reducing the expression of pro-inflammatory cytokines and inhibiting the local proliferation of Th17 cells." (PMID 34868054, 2021). "IL-10 concentrations were statistically significant decreased in the periodontitis group compared to those periodontally healthy (2.0 ± 1.0 vs. 3.0 ± 1.2 pg/mL, P = 0.002)." (PMID 33441852, 2021). "In this way, when periodontitis becomes chronic, negative regulation of inflammation through the anti-inflammatory cytokines IL-4, IL-6, IL-10, IL-11, and IL-13 becomes predominant." (PMID 34707462, 2021). "In the case of periodontitis, increased accumulation of Tregs capable of producing IL-10 suppressed the inflammation in periodontal tissue." (PMID 33562334, 2021). "In the present review, we revise and discuss the pathogenic characteristics of NKT cells in these diseases and their role in the pathogenesis of periodontitis; particularly, we analyze the potential regulatory role of the IL-10-producing NKT10 cells." (PMID 34594157, 2021). "PISA (a measure of active periodontitis) was positively correlated with inflammatory markers whilst the opposite was found with IL-10." (PMID 33441852, 2021).